RNU6-84P (RNA, U6 small nuclear 84, pseudogene)
Gene: Small nuclear RNA gene on chromosome 6 (76,557,653 to 76,557,754, reverse strand). Ensembl gene ENSG00000272445.
Homologues: Orthologues: chimpanzee U6 (100% identical), pig U6 (83% identical), mouse Gm25558 (71% identical). Paralogues in human: RNU6-38P (89% identical), RNU6-28P (87% identical), RNU6-40P (87% identical), RNU6-1 (86% identical), RNU6-2 (86% identical), RNU6-29P (86% identical), RNU6-39P (86% identical), RNU6-3P (86% identical), RNU6-46P (86% identical), RNU6-4P (86% identical), RNU6-5P (86% identical), RNU6-6P (86% identical), and 1287 more.